MMP13 (matrix metallopeptidase 13)
Diseases named in the same sentence as MMP13 in open-access papers (continued):
Sharing a sentence is not in itself a finding about the gene and the disease.
osteoarthritis (continued). "The potent pro-inflammatory cytokine interleukin-1β (IL-1β) modulates MMP13 expression and is therefore a critical cytokine during osteoarthritis progression." (PMID 36672165, 2023). "Our findings revealed MIA/CD-RAP as a new regulator of MMP13 and highlighted its role as a potential new target for osteoarthritis therapy." (PMID 36672165, 2023). "The current study, therefore, makes several contributions to the understanding of MMP13 expression in the development of osteoarthritis." (PMID 37237597, 2023). "DUSP1 has a protective effect on osteoarthritis by intercepting the expression of MMP-13 and activating the MAPK pathway." (PMID 36681837, 2023). "Other authors described the role of MMP-13 in the progression of osteoarthritis, suggesting that MMP-13 is primarily involved in the development of pain in patients with OA." (PMID 36830637, 2023). "MMPs are responsible for the degradation of the extracellular matrix protein COL2A1, in which MMP13 is a dominant player in the progression of osteoarthritis." (PMID 37525533, 2023). "Real-time PCR analysis revealed PRF or HA treatment also significantly repressed the expression of catabolic mediators including Adamst5 and Mmp13, inhibition of which would protect from osteoarthritis progression." (PMID 38144541, 2023). "Mg can reduce the loss of type II collagen and glycosaminoglycan in osteoarthritis, and can inhibit the expression of interleukin-1β (IL-1β), Tumor Necrosis Factor-α (TNF-α), and matrix metalloproteinase 13 (MMP13) in osteoarthritis." (PMID 36546928, 2022). "Increased ALK1/ALK5 ratio has also been seen to correlate with MMP13 expression in age-dependent osteoarthritis." (PMID 35897723, 2022). "In view of the biological activity of MMP13, it has become an attractive target for the treatment of osteoarthritis, cancer, and cardiovascular diseases." (PMID 35449811, 2022). "MMP13 is known to be a positive indicator of osteoarthritis and other cartilage degeneration; it has a role in the degradation of collagen in the matrix." (PMID 35269204, 2022). "Recently, a Smo‐specific inhibitor named taladegib was verified to be a promising agent for osteoarthritis treatment, since it controlled chondrocyte hypertrophy by down‐regulating the expression of MMP13, collagen type X and RUNX2 via Smo/Gli1 signalling." (PMID 34918401, 2022). "Similar osteoclast defects were observed in medaka embryos treated with the MMP13 inhibitor CL-82198 hydrochloride, which had earlier been used for the treatment of osteoarthritis." (PMID 35281094, 2022). "Elevated IL-7 enhances MMP-13 production in osteoarthritis patients, which has a significant effect in degenerative diseases." (PMID 36186138, 2022). "This is because, IL-7 stimulates the secretion of S100A4, which has been verified to be elevated in osteoarthritis and upregulates the expressions of MMP13 by activating the JAK/STAT pathway." (PMID 36186138, 2022). "S100A4 has been found to be upregulated in osteoarthritis chondrocytes (also in our study log2FC = 0.8, P = 1.9 × 10−15) and has been proposed to be a transcriptional regulator of MMP13, which is a key metalloprotease of extracellular matrix degradation." (PMID 35088088, 2022). "We observed that the MMP-13 content of knee-joint synovial membrane was significantly higher in the osteoarthritis group than in the control group." (PMID 35496642, 2022). "MMP13 is synthesized by articular chondrocytes and plays an important role in the ECM degradation of articular cartilage associated with osteoarthritis (OA)." (PMID 34502142, 2021). "In the pathogenesis of osteoarthritis, the matrix-degrading enzymes MMP-13 and ADAMTS-5 play a role." (PMID 34868573, 2021). "In humans, MMP-13 is highly overexpressed in patients with rheumatoid arthritis, osteoarthritis, and lymphangiogenesis of multiple myeloma." (PMID 34072157, 2021).
osteoarthritis (continued). "The addition of Wharton’s jelly to synoviocytes isolated from human knees with grade IV osteoarthritis reduced the expression of MMP-13 and RELA." (PMID 34832872, 2021). "In this review, the databases used were PubMed and Google Scholar with appropriate keywords (osteoarthritis, pathogenesis, cartilage degradation, MMP-13, epigenetic regulation, and synthetic inhibitor)." (PMID 33572320, 2021). "MMP-8 is responsible for the increase in cytokines observed during inflammatory processes and MMP-13 participates in osteoarthritis, which is initiated by an inflammatory process." (PMID 34830409, 2021). "In conclusion, we have identified 9a as a water-soluble and highly potent MMP-13 inhibitor, which constitutes a new promising candidate for the treatment of osteoarthritis and related diseases." (PMID 34576138, 2021). "This disturbance in the lipid metabolism of chondrocytes is linked with pro-inflammatory events in osteoarthritis and in turn the biosynthesis of key players such as VEGF, MMP-13 and MMP-8, which regulate bone formation." (PMID 34830409, 2021). "The percentage of methylated CpG sites of these MMP genes in clonal chondrocytes from osteoarthritis patients versus controls were: 80% versus 96% for MMP13, 19% versus 53% for MMP9, and 43% versus 70% for MMP3." (PMID 33920915, 2021). "In a murine model of osteoarthritis, intra-archaeal injection of IL-36Ra alleviated osteoarthritis by interfering with IL-36R signalling and MMP-13 expression." (PMID 34365521, 2021). "TNF-α’s activity blockade through soluble PEGylated TNFR1 was shown to decrease the production of MMP-1, MMP-3 and MMP-13 in femoral condylar cartilage cells cultured from osteoarthritis patients." (PMID 34201546, 2021). "Core binding factor-β was highly expressed in the osteoarthritis cartilage (p < 0.001), and MMP-13, IL-1β, COMP and YKL-40 expression were greater than found in normal cartilage (p < 0.001)." (PMID 33573620, 2021). "Cartilage tissues, from healthy subjects and patients with osteoarthritis, were collected for histology and expression of Core binding factor-β, MMP-13, IL-1β, COMP, and YKL-40." (PMID 33573620, 2021). "In patients with osteoarthritis, MMP-13 is the main member of MMP family expressed in cartilage, but not in normal adults." (PMID 33461534, 2021). "The involvement of MMP-13 in the pathogenesis of osteoarthritis was demonstrated by altering the physiological and anatomical functions of the joints." (PMID 33419373, 2020). "These compounds were tested for the treatment of osteoarthritis and indeed presented selectivity against MMP-13." (PMID 32380782, 2020). "MMP-3, MMP-9, and MMP-13 levels increased in animals induced with osteoarthritis, but the TIMP-2 level was shown to decline." (PMID 32189997, 2020). "In osteoarthritis, MMP13 was highly expressed in chondrocytes and synovial cells responsible for the degradation of cartilage matrix." (PMID 32351957, 2020). "In development of osteoarthritis drugs, the pyrimidine-2,4,6-trione inhibitors have been optimized to inhibit MMP-13." (PMID 32380782, 2020). "Such a pathological mechanism has been proposed for MMP-3 and MMP-13 in degenerative joint disease in the elderly." (PMID 32116759, 2020). "Several biphenyl sulfonamide carboxylate MMP inhibitors were designed to treat osteoarthritis by inhibiting MMP-13." (PMID 33419373, 2020). "For instance, a positive relationship has been identified between RELA expression and MMP-13 expression, a cytokine involved in cartilage degradation, in synoviocytes affected by osteoarthritis." (PMID 33207573, 2020). "Several transcription factors regulate expression of MMP13, which plays an important role in endochondral ossification and the onset of osteoarthritis." (PMID 32079226, 2020). "Mmp13 is recognized as a potential target for bone resorption related diseases, such as osteoarthritis and periapical periodontitis." (PMID 31088450, 2019).
osteoarthritis (continued). "The levels of collagen II, aggrecan, and MMP-13 in chondrocytes have been found to be dysregulated in degenerative joint diseases including OA, and these abnormal expression patterns can therefore be regarded as biomarkers of chondrocyte function." (PMID 30949498, 2019). "In osteoarthritis (OA), miR-411 was repressed by IL-1β treatment in OA cartilage, directly targeted MMP-13 to inhibit chondrocyte cell proliferation, and increased expression of type II and type IV collagen." (PMID 30390072, 2019). "MMP13 expression and down-regulation of type II collagen in chondrocytes, both of which indicate osteoarthritis, as well as chondrocyte apoptosis in osteoarthritis rats were inhibited by NAC." (PMID 31822750, 2019). "We observed that osteoarthritis, based on MMP13 expression and induction of apoptosis of chondrocytes, developed spontaneously even on the sham-operated sides." (PMID 31822750, 2019). "On the other hand, overexpression of MMP13 seems to be involved in different bone resorbing diseases like osteoarthritis and formation of osteolytic lesions due to multiple myeloma and breast cancer." (PMID 31831031, 2019). "MMP-3 and MMP-13 have been found in increased levels at the sites of cartilage erosion in cases of rheumatoid arthritis and osteoarthritis." (PMID 30691120, 2019). "The aim of this study was to investigate the role of Notch signaling changes during proliferation and differentiation of chondrocyte, and to testify the mechanism of MMP-13 regulation by Notch and Runx2 expression changes during osteoarthritis." (PMID 31666602, 2019). "Expression of MMP13, a marker of osteoarthritis development, in chondrocytes in vivo was inhibited by oral NAC administration, and reduced type II collagen expression in articular cartilage was rescued by NAC treatment in vivo." (PMID 31822750, 2019). "We transfected human osteoarthritis chondrocytes with an miR-448 mimic or inhibitor, expressions of matrilin-3, aggrecan, type II collagen and MMP-13 were determined using western blot, quantitative real-time PCR and ELISA assays as appropriate." (PMID 29483929, 2018). "The previous study also showed the association of MMP-13 expression with ALK1 expression suggesting them as key molecules of chondrocyte hypertrophy and osteoarthritis." (PMID 29731966, 2018). "ELF3 levels are elevated in human cartilage from patients with osteoarthritis (OA), and ELF3 contributes to the IL-1β-induced expression of genes encoding Mmp13, Nos2, and Ptgs2/Cox2 in chondrocytes in vitro." (PMID 29691435, 2018). "The previous experiment suggested the involvement of IL6 in osteoarthritis progression through MMP13, which is further established in current study showing IL6 as upregulated DEG in both virus and σB treated group." (PMID 29731966, 2018). "Knockdown of miR-448 significantly increased the expressions of matrilin-3, aggrecan and type II collagen, and decreased the expression of MMP-13 compared with osteoarthritis chondrocytes transfected with anti-miR-NC." (PMID 29483929, 2018). "ELF3 protein is overexpressed in the cartilage of patients with osteoarthritis, and drives expression of the IL-1β-induced genes MMP13, NOS2, and PTGS2/COX2 in chondrocytes." (PMID 30200227, 2018). "Studies have shown that the degradation of components (mainly composed of collagen) was increased in patients with osteoarthritis, while MMP13 involved in the degradation of collagen was significantly increased." (PMID 29113082, 2017). "Compared with the control group, the mRNA and protein levels of MMP1, MMP3, and MMP13 increased significantly in IL-1β-stimulated human osteoarthritis chondrocytes." (PMID 29179489, 2017). "We observed that upregulation of miR-144-3p, induced by peroxisomal dysfunction, stimulates apoptosis and MMP13 induction during osteoarthritis pathogenesis." (PMID 29050208, 2017).
osteoarthritis (continued). "MMP-13 belongs to the matrix metalloproteinase family and is highly overexpressed in pathological situations such as human carcinomas, osteoarthritis and rheumatoid arthritis." (PMID 28498809, 2017). "Matrix metalloproteinase (MMP)-13 is a major contributor to cartilage degradation in osteoarthritis (OA)." (PMID 28798419, 2017). "Degradation of collagen type II by collagenase-1 and collagenase-3 (also called MMP-13) represents one of the biochemical hallmarks of osteoarthritis." (PMID 28275210, 2017). "Specific MMPs, such as MMP-1 (collagenase-1), MMP-3 (stromelysin-1), and MMP-13 (collagenase-3), degrade cartilage proteoglycans and type II collagen, leading to osteoarthritis." (PMID 29348767, 2017). "Particularly telling and supporting its utility as a biomarker in osteoarthritis is the tendency of external influences to act upon the joint through upregulation of MMP-13 specifically, as will be discussed in further detail later in this review." (PMID 27478294, 2016). "Nevertheless, we look to one in particular, MMP-13, as the principal effector of cartilage degradation in osteoarthritis and the most obvious and useful candidate for matrix metalloproteinases as a biomarker in the disease." (PMID 27478294, 2016). "Previous studies showed that the upregulation of MMP-13 occurs during chondrogenic differentiation, and MMP-13 has been found to be upregulated in patients with osteoarthritis, suggesting a pathological role of MMP-13 in the disease process." (PMID 27612636, 2016). "Having such a unique and dramatic effect on said tissue, it is obvious why MMP-13 is frequently employed as the matrix metalloproteinase of choice in the detection and study of osteoarthritis." (PMID 27478294, 2016). "It is highly likely that pharmacologic intervention of osteoarthritis will target upstream of MMP-13 expression." (PMID 27478294, 2016). "MMP13 is a collagenase, which is considered to perform a key role in the non-reversible destruction of the type II collagen network in cartilage during osteoarthritis." (PMID 26853752, 2016). "Chondrocyte hypertrophy, regulated by Runt-related transcription factor 2 (RUNX2) and matrix metalloproteinase 13 (MMP13), is a crucial step in cartilage degeneration and osteoarthritis (OA) pathogenesis." (PMID 27563877, 2016). "The body of evidence implicates MMP-13 as a major effector of mechanically mediated joint destruction in osteoarthritis." (PMID 27478294, 2016). "It appears to be correlated with osteoarthritis as well, with intervention at the level of MMP-13 expression occurring." (PMID 27478294, 2016). "MMP-13 is a collagenase and has a predominant role in osteoarthritis due to its contribution to collagen degradation." (PMID 26762166, 2016). "Among the MMPs, MMP-3 and MMP-13 are known to play crucial role in osteoarthritis cartilage destruction." (PMID 26208633, 2015). "MMP-13 is usually produced only by cartilage and bone during development, and by chondrocytes in osteoarthritis, and hydrolyzes type II collagen more efficiently than the other collagenases." (PMID 25837977, 2015). "In osteoarthritis, chondrocytes adopt an abnormal hypertrophic morphology and upregulate the expression of the extracellular matrix-degrading enzymes, MMP-13 and ADAMTS-5." (PMID 26705100, 2015). "It has been reported that CREB promotes the expression of MMP-13 in human articular chondrocytes and osteoarthritis." (PMID 26378022, 2015). "Serum and synovial levels of MMP1, MMP3 and MMP13 are increased in rheumatoid arthritis and osteoarthritis." (PMID 24739658, 2014). "Our results provide evidence that AREG acts through the EGFR and activates PI3K, Akt, and finally NF-kappaB on the MMP-13 promoter, thus contributing to cartilage destruction during osteoarthritis." (PMID 25147440, 2014).
osteoarthritis (continued). "Previous observations implicate Indian hedgehog (Ihh) signaling in osteoarthritis (OA) development because it regulates chondrocyte hypertrophy and matrix metallopeptidase 13 (MMP-13) expression." (PMID 24428864, 2014). "MMP13, a key marker of chondrocyte hypertrophy, is proving a critical target in osteoarthritis research due to its potent role in the degradation of collagen type-II, proteoglycans, collagen types-IV and IX, osteonectin and perlecan." (PMID 23959079, 2013). "Most importantly, the expressions of key proinflammatory genes such as Il6, Vcam1, Ccl7, Mmp3, Mmp13, enhanced in rheumatoid arthritis and osteoarthritis, were reduced." (PMID 24199619, 2013). "Deletion of the Mmp13 gene specifically in chondrocytes also produces similar deceleration of osteoarthritis disease progression following meniscal-ligamentous injury in a mouse model." (PMID 23959079, 2013). "We intentionally included key proinflammatory mediators, genes of matrix metalloproteinase (Mmp3, Mmp13), which are known to degrade collagen in cartilage and thereby enhance rheumatoid arthritis and osteoarthritis progression." (PMID 24199619, 2013). "MMP13 level and activity are enhanced in correlation with the degenerative changes in osteoarthritis cartilage and this molecule co-localizes with its specific type II collagen cleavage products." (PMID 23637839, 2013). "Consistent with this crucial role for Mmp13, its overexpression was also found to result in pathological osteoarthritis-like changes in the articular cartilage of mice." (PMID 23959079, 2013). "The present study investigated the effects of an aqueous extract of Eucommia on the articular cartilage (by Mankin’s grade) and the levels of matrix metalloproteinase-1 (MMP-1), MMP-3 and MMP-13 in the serum and synovial fluid in a rat model of osteoarthritis." (PMID 24137247, 2013). "MMP-13 has a key role in the MMP activation cascade and appears to be critical in bone metabolism, homeostasis, osteoarthritis, and rheumatoid arthritis, but is also highly associated with tumor invasion and metastasis." (PMID 21461405, 2011). "MMP-13 is expressed in articular cartilage and joints of osteoarthritis (OA) and rheumatoid arthritis (RA) patients, respectively, but not in normal adult tissues." (PMID 20824169, 2010). "TauCl also differentially inhibits the expression of MMP-1 and MMP-13, which play dominant roles in RA and osteoarthritis (OA), in IL-1β-stimulated fibroblast-like synoviocytes (FLS)." (PMID 20804602, 2010). "The levels of adiponectin, VEGF, MMP-1, and MMP-13 in the joint fluids from 30 RA or osteoarthritis (OA) patients were also measured." (PMID 19883500, 2009). "MMP13 is one of the major pathophysiological mediators of cartilage destruction, through degradation of type II collagen in osteoarthritis and therefore its down-regulation is of great clinical importance." (PMID 19011694, 2008). "At lower concentrations of TauCl, inhibition of MMP-13 expression would be a potentially effective strategy to control the destruction of joint cartilage in RA and osteoarthritis." (PMID 17697361, 2007). "The MMP-1 and MMP-13 collagenases play dominant roles in RA and osteoarthritis because they are rate-limiting components of the collagen degradation process." (PMID 17697361, 2007). "Matrix metalloprotease (MMP)-13 plays an important role in cartilage degradation in osteoarthritis (OA)." (PMID 16507124, 2006). "The mechanism of endothelin-1 (ET-1)-induced nitric oxide (NO) production, MMP-1 production and MMP-13 production was investigated in human osteoarthritis chondrocytes." (PMID 15743480, 2005). "MMP-13 is a key mediator of articular cartilage degeneration in osteoarthritis." (PMID 39935926, 2025).